AR (androgen receptor)
Diseases named in the same sentence as AR in open-access papers (continued):
Sharing a sentence is not in itself a finding about the gene and the disease.
metastatic prostate carcinoma (continued). "This is supported by our clinical data demonstrating WDR62 levels are not correlated with AR levels in metastatic prostate cancer." (PMID 34326322, 2021). "The treatment of advanced or metastatic prostate cancer (PCa) is focussed around androgen deprivation therapy (ADT), as testosterone and dihydrotestosterone promote neoplastic behaviour of PCa cells through androgen receptor (AR) signalling." (PMID 32989230, 2020). "Although miR-186-5p was also up-regulated in non-metastatic and metastatic prostate cancer cell lines, miR-186-5p levels did not vary by androgen receptor status." (PMID 29653561, 2018). "It should be noted that the mRNA expression of DNAH8 and AR were not significantly correlated in the metastatic prostate cancer cases (p = 0.45." (PMID 27363033, 2016). "Guidelines currently recommend the early use of second-generation androgen receptor signaling inhibitors (ARSIs) in both castrate-resistant and -sensitive metastatic prostate cancer (with or without chemotherapy) and also in biochemical non-metastatic castrate-sensitive relapse." (PMID 42206285, 2026). "Using SCellBOW, we identified a hitherto unknown and pervasive AR−/NElow (androgen-receptor-negative, neuroendocrine-low) malignant subpopulation in metastatic prostate cancer with conspicuously high aggressiveness." (PMID 40511682, 2025). "In this Surveillance, Epidemiology, and End Results‐Medicare based study of older adults with metastatic prostate cancer, both polypharmacy and nonadherence to androgen receptor signaling inhibitors were common and independently associated with increased acute care use." (PMID 41176642, 2025). "Interestingly, apelin expression was higher in metastatic prostate cancer (androgen receptor [AR] positive) compared to nonmetastatic disease." (PMID 36291151, 2022). "Collectively, these findings demonstrate that inhibition of neutrophilic ROS induces death of AR-negative (PC3, PAIII), with little impact on AR-positive (C42B, RM1), castration-resistant metastatic prostate cancer." (PMID 35604506, 2022). "Hormone therapy is the current primary treatment for metastatic prostate carcinoma, which implies the lack of circulating testosterone to activate the androgen receptor (AR) in tumor cells, and it may be accomplished by a reduction in testosterone production or by AR blockade." (PMID 24527078, 2014). "This aptamer was then tested on cells that were androgen receptor (AR)-negative (PC3) and AR-positive (LNCaP and 22Rv1), because ARs may suppress metastatic potential and are often upregulated in patients with metastatic prostate cancer." (PMID 29301363, 2018).
androgen insensitivity syndrome (198 papers, 2007 to 2026). Androgen insensitivity syndrome (AIS) is a disorder of sex development (DSD) characterized by the presence of female external genitalia, ambiguous genitalia or variable defects in virilization in a 46,XY individual with absent or partial responsiveness to age-appropriate levels of androgens. "Complete androgen insensitivity syndrome (CAIS) is caused by pathogenic variants in the androgen receptor (AR) gene that lead to a phenotypically female appearance in XY individuals." (PMID 41970947, 2026). "A novel AR frameshift mutation (c.2023_2035del) was identified in a 17-year-old phenotypic female with Complete Androgen Insensitivity Syndrome (CAIS)." (PMID 42137628, 2026). "AR coding mutations have been implicated in androgen insensitivity syndromes and are found in cases of severe hypospadias and ambiguous genitalia, but have been found by some to be uncommon in isolated hypospadias." (PMID 41596366, 2026). "Variants in the androgen receptor (AR) gene cause androgen insensitivity syndrome (AIS), ranging from complete (CAIS) to partial (PAIS) and mild (MAIS) forms." (PMID 41142184, 2025). "Among these are specific polymorphisms of the AR, which influence susceptibility to PCa and are implicated in impaired spermatogenesis, particularly in cases of hereditary androgen insensitivity syndrome, a recognized cause of male infertility." (PMID 41327353, 2025). "Complete androgen insensitivity syndrome (CAIS) is a rare X-linked recessive disorder of sex development (DSD) caused by androgen receptor (AR) gene mutation and present with female phenotypes with male chromosomal karyotype." (PMID 41163677, 2025). "Among the most frequently mutated genes in this meta-analysis, androgen receptor (AR) gene mutations are known to cause androgen insensitivity syndrome." (PMID 41401169, 2025). "Abnormal levels of total and LDL cholesterol and impaired insulin sensitivity were present in a large subset of patients with complete androgen insensitivity syndrome, which is caused by loss-of-function mutations in the androgen receptor gene." (PMID 40290009, 2025). "The androgen receptor (AR) gene is encoded on X chromosome and can carry hundreds of mutations causing Complete Androgen Insensitivity Syndrome (CAIS)." (PMID 38212646, 2024). "Androgen insensitivity syndrome (AIS) is a rare Mendelian disorder caused by mutations of the androgen receptor (AR) gene on the long arm of the X chromosome." (PMID 38398243, 2024). "The androgen receptor (AR) gene, whose mutations cause androgen insensitivity syndrome and spermatogenic damage, and the CFTR gene, whose mutations cause cystic fibrosis and loss of vas deferens, both play important roles in gonadal differentiation." (PMID 39055413, 2024). "A de novo pathogenic variant (p.S426*) in the AR gene was observed in two sisters who presented complete androgen insensitivity syndrome (CAIS)." (PMID 36631813, 2023). "Historically, lower molecular weight (LMW) AR variants have been reported in studies on AR in androgen insensitivity syndrome and in malignancies, but their role in PCa was established only about a decade ago." (PMID 37626712, 2023). "Mutations in the AR sequence can cause numerous physiological disorders, such as partial and complete androgen insensitivity syndromes, that lead to abnormal sexual development." (PMID 36979886, 2023). "Androgen insensitivity syndrome (AIS) is caused by abnormal androgen receptor (AR) genes that show variable genotypes and phenotypes." (PMID 35974208, 2023). "A pathogenic variant in AR can cause androgen-insensitivity syndrome (AIS), which has undermasculinization of the external genitalia and impaired spermatogenesis, while hypospadias/CAVD patients have normal spermatogenesis." (PMID 36437957, 2022). "Androgen insensitivity syndrome (AIS) is a rare inherited condition caused by X-linked pathogenic mutations in the androgen receptor (AR) gene." (PMID 35353710, 2022).
androgen insensitivity syndrome (continued). "When this mutation occurs, Complete Androgen Insensitivity Syndrome (CAIS) can result from production of an uORF which ablates AR protein production." (PMID 35213597, 2022). "Mutations in the AR gene are the main reason of androgen insensitivity syndrome (AIS), which is divided into complete (CAIS), partial (PAIS), and mild (MAIS) according to the degree of feminization of patients." (PMID 36159980, 2022). "Men with complete androgen insensitivity syndrome owing to loss of function mutations in AR gene have diminished vertebral and femoral bone density, supporting a seminal role for the AR in the accrual and/or maintenance of bone density." (PMID 35136023, 2022). "Disorders in androgen action arise with mutation in the androgen receptor that result in the Androgen insensitivity syndrome or endocrine disruptors that interact with androgen action." (PMID 35220478, 2022). "Complete Androgen Insensitivity Syndrome (CAIS) is a rare genetic condition by mutations in the androgen receptor (AR) gene resulting in target issue resistance to androgens and a female phenotype in genetically male individuals." (PMID 36553343, 2022). "This novel nonsense mutation adds to the compendium of AR mutations which result in complete androgen insensitivity syndrome (AIS)." (PMID 34471093, 2021). "The mutation also leads to a partial loss of AR function, which accounts for certain aspects of the disease, such as the partial androgen insensitivity syndrome frequently observed in patients with SBMA." (PMID 34417184, 2021). "Androgen insensitivity syndrome is a rare X-linked disorder of sex development, caused by mutations in the androgen receptor." (PMID 33863387, 2021). "The phenotypes of 46, XY individuals with AR gene mutations are categorized as complete androgen insensitivity syndrome (CAIS) or PAIS, respectively, and the more severe forms belong to disorders of sex determination." (PMID 34276780, 2021). "Loss-of-function mutations in the AR gene (located on the X chromosome) cause the dysregulation of the AR signaling pathway, resulting in androgen insensitivity syndrome (AIS) in 46,XY individuals." (PMID 33182400, 2020). "The equine androgen insensitivity syndrome was also proposed as a genetic etiology due to association of familial sequence variants in the AR-gene segregating among carrier mares and affected stallions." (PMID 31936796, 2020). "Complete androgen insensitivity syndrome (CAIS, also referred to as Morris syndrome) which is an X-linked disorder affecting genetically males (46,XY) caused by hemizygous mutations in the androgen receptor gene, AR (OMIM #300068)." (PMID 32819397, 2020). "Mutations in the AR gene cause complete, partial or mild androgen insensitivity syndrome depending on the type and the location of the mutation in the gene." (PMID 32155011, 2020). "We identified novel mutations in the androgen receptor DNA sequence as well as in the CYP11A1 gene in individuals with clinically diagnosed Complete Androgen Insensitivity Syndrome." (PMID 31671693, 2019). "Differential diagnosis includes isolated vaginal atresia, androgen insensitivity syndrome caused by mutations of the androgen receptor gene (AR) in XY individuals and WNT4 defects characterised by MRKH and hyperandrogenism." (PMID 29527097, 2018). "Partial androgen insensitivity syndrome developed in this case, probably because of the presence of the heterozygous AR mutation concurrent with random X inactivation of the healthy allele." (PMID 29022558, 2018). "In androgen receptor (AR), many mutations are associated with androgeninsensitivity syndrome, which leads to malformation of genitalia both in male andfemale." (PMID 28945216, 2017). "Men with androgen insensitivity syndrome caused by AR gene mutations have a higher risk of developing TC." (PMID 26885616, 2016).
androgen insensitivity syndrome (continued). "Only approximately 85% of patients with a clinical diagnosis complete androgen insensitivity syndrome and less than 30% with partial androgen insensitivity syndrome can be explained by inactivating mutations in the androgen receptor (AR) gene." (PMID 27583472, 2016). "Mutations in the X-linked androgen receptor (AR) gene underlie complete androgen insensitivity syndrome (CAIS), the most common cause of 46,XY sex reversal." (PMID 27609317, 2016). "In fact, subjects with SBMA often exhibit certain symptoms of androgen insensitivity syndrome, such as gynecomastia and reduced fertility, which have been attributed to loss of AR function." (PMID 28005993, 2016). "Here we describe a recurrent germline mutation found in two unrelated patients with complete androgen insensitivity syndrome (CAIS) generating an upstream open reading frame (uORF) in the 5’ untranslated region (5’-UTR) of the androgen receptor (AR) gene." (PMID 27110943, 2016). "The AR has an important role in the homeostasis of the male skeleton with idiopathic hypogonadotropic hypogonadism or complete androgen insensitivity syndrome because of a loss-of-function mutation in AR having low bone mass." (PMID 25147565, 2014). "In the third category, androgen receptor (AR) mutations have been identified in patients with mild, partial or complete androgen insensitivity syndromes (AIS)." (PMID 24885102, 2014). "Of the exon 1 mutations described in the AR database, 70% induced complete androgen insensitivity syndrome (CAIS), 14% induced partial androgen insensitivity syndrome (PAIS), and 16% were implicated in infertility." (PMID 23637914, 2013). "Alterations in the androgen sensitivity pathway have been identified in severely undermasculinized boys, and mutations of the androgen receptor gene (AR) are usually found in partial or complete androgen insensitivity syndrome (AIS)." (PMID 23637914, 2013). "We report here the novel p.L830F mutation in the hormone binding region of the androgen receptor that is responsible for partial androgen insensitivity syndrome in a Brazilian family." (PMID 21645389, 2011). "Androgen insensitivity syndrome (AIS) is a rare disease associated with inactivating mutations of AR that disrupt male sexual differentiation, and cause a spectrum of phenotypic abnormalities having as a common denominator loss of reproductive viability." (PMID 20011049, 2009). "Previously, we have identified global gene expression profiles in genital-derived fibroblasts that differ between 46, XY males and 46, XY females with complete androgen insensitivity syndrome (CAIS) due to inactivating mutations of the androgen receptor (AR)." (PMID 17945006, 2007). "We tested this hypothesis using a mutant form of AR that encodes an amino acid substitution in the DNA recognition helix (V582F) that results in loss-of-function and complete androgen insensitivity syndrome." (PMID 40681873, 2025). "Furthermore, a DHX37 variant instead of an AR variant was identified in a patient clinically diagnosed with complete androgen insensitivity syndrome." (PMID 40247401, 2025). "The androgen insensitivity syndrome is caused by mutations in the androgen receptor gene." (PMID 41180762, 2025). "Androgen insensitivity syndrome is an X-linked inheritance with a mutation in the AR gene." (PMID 37485217, 2023). "Furthermore, several mutants of AR that are causative of androgen insensitivity syndrome, including Pro767 mutated to Ala, remain as monomers even in the presence of DHT." (PMID 34057812, 2022). "Considering the finding that androgen receptor (Ar) is known to be associated with androgen insensitivity syndrome (AIS) and that a lot of mutations with unknown functions have been reported in human patients, we decide to target Ar using the two CBEs." (PMID 35300420, 2022).
androgen insensitivity syndrome (continued). "An interesting case study reported that a woman carrying a heterozygous AR gene mutation gave birth to a baby with androgen insensitivity syndrome suggesting plausible repercussions on reproductive outcomes associated with AR gene mutations and not only with repeat lengths." (PMID 29670770, 2018). "Interestingly, a germline mutation S650G of AR results in the mild androgen insensitivity syndrome associated with male infertility and moderately reduced reporter transactivation in vitro." (PMID 25950519, 2015). "Remarkably, unique natural human models to distinguish chromosomal and hormonal influences are disorders of sex development (DSD), in particular the androgen insensitivity syndrome (AIS) in which inactivating mutations in the AR-gene abolish the AR-signaling pathway." (PMID 24023855, 2013). "To this end, we performed large scale array-based analysis of gene methylation profiles on genomic DNA from labioscrotal skin fibroblasts of 8 males and 26 individuals with androgen insensitivity syndrome (AIS) due to inactivating androgen receptor gene mutations." (PMID 24023855, 2013). "Mutations affecting the AR gene may cause either complete or partial androgen insensitivity syndrome." (PMID 21902827, 2011). "In a previous genome-wide assessment of transcript profiles, we have identified transcripts differentially expressed in cultured genital fibroblasts from normal males and 46,XY females with androgen insensitivity syndrome due to inactivating androgen receptor mutations." (PMID 19570224, 2009). "Similarly, studies on androgen insensitivity syndrome associated androgen receptor Pro-892-Ala and Pro-892-Leu mutations revealed via biochemical assays and MD simulations an increased flexibility and distortion of the αAF helix." (PMID 18617990, 2008). "Interestingly, in human, mutations of the AR gene represent the molecular basis of androgen insensitivity syndrome (AIS)." (PMID 19094205, 2008). "Disruption of this signaling through inactivating mutations of AR can lead to androgen insensitivity syndromes (AIS), in which genotypic males are affected by a spectrum of developmental abnormalities of the genital apparatus and of the secondary sexual characteristics." (PMID 18978937, 2008). "Androgen insensitivity syndrome (AIS) is a disorder caused by pathogenic mutations in the androgen receptor (AR) gene, leading to androgen resistance and impaired sex differentiation in 46,XY individuals." (PMID 42021352, 2026). "However, it is tempting to speculate that loss-of-function mutations in AR leading to complete androgen insensitivity syndrome (CAIS) cause obesity and metabolic syndrome due to the upregulation of ACBP/DBI." (PMID 40011442, 2025). "X-linked loss-of-function mutations in AR are the predominant cause of androgen insensitivity syndrome (AIS), a prototypical SC-related disorder/difference of sex development (DSD)." (PMID 41450735, 2025). "Mutations of the androgen receptor (AR) gene result in varied entities of androgen insensitivity syndrome (AIS), from subtle spermatogenic failure to complete testicular feminization." (PMID 41465244, 2025). "Mutations in the AR gene have been implicated in conditions which affect body composition, including androgen insensitivity syndrome (AIS) and Spinal and Bulbar Muscular Atrophy (SBMA) (ie., Kennedy’s Disease)." (PMID 40269952, 2025). "The critical role of the AR as a molecular switch is confirmed by 46,XY DSD individuals who have inactivating mutations of the X-chromosomal AR-gene leading to the androgen insensitivity syndrome (AIS)." (PMID 38840820, 2023). "Androgen insensitivity syndrome (AIS) is an X-linked recessive genetic disorder caused by mutation in the androgen receptor." (PMID 35220478, 2022).